CD163 (CD163 molecule)
Diseases named in the same sentence as CD163 in open-access papers (continued):
Sharing a sentence is not in itself a finding about the gene and the disease.
tumor (1,991 papers, 2007 to 2026). "For example, the cancer-associated fibroblast regulator NNMT, CD163, a marker of tumor-associated macrophages (TAMs), and oncogenic proteoglycan VCAN were significantly upregulated from the NFT stroma to the invasive stroma." (PMID 41233595, 2026). "We report a population of high FOLR1-expressing tumor-associated macrophages (CD163 + FOLR1 + ), suggesting potential on-target, off-tumor immune editing by MIRV." (PMID 41888141, 2026). "In colorectal cancer, enrichment of CD163+ TAMs is associated with higher tumor grade, increased expression of epithelial–mesenchymal transition markers, and T‐cell exhaustion." (PMID 41426206, 2026). "AGR2 is predominantly expressed in CD163+ M2-like tumor-associated macrophages (TAMs), with levels rising alongside tumor stage." (PMID 41836390, 2026). "ERO1A expression was positively correlated with the density of infiltrating CD163+ tumor-associated macrophages (TAMs) in ccRCC." (PMID 41809819, 2026). "This is further supported by the up-regulation of serum markers such as CD163, associated with tumor-associated macrophages, alongside the elevated expression of tumor progression and microenvironment regulation markers in colon tissue." (PMID 40476597, 2025). "In contrast, some EAC cases present a largely inflamed phenotype, characterized by a high and low number of immune cells, such as CD8 and CD163-positive T cells, respectively, which exhibit anti-tumor effects associated with better outcomes and prognosis." (PMID 41369383, 2025). "CD163 is a well-established marker for identifying monocyte-derived macrophages, including in tumors, where they form part of the population of tumor-associated macrophages (TAMs)." (PMID 40136662, 2025). "Since IBA1 is known to label both phagocytic microglia and full-blown brain macrophages in brain pathologies, our finding of a strikingly different pattern of expression of IBA1 and CD163 in association with tumor necrosis was surprising." (PMID 40191733, 2025). "Our findings highlight a compelling link between circulating bile acids and immune modulation, as GCDCA was shown to promote monocyte differentiation into CD163+ tumor-associated macrophages, which exhibit pro-tumorigenic properties." (PMID 40476597, 2025). "CD163 is a hallmark of tumor-associated macrophages, which are known to support tumor initiation, progression, and metastasis through their immunosuppressive and pro-angiogenic properties." (PMID 40476597, 2025). "Patients were divided into M2 low and M2 high groups, and the cutoff was set at 75% of CD163-positive cells of tumor-associated macrophages." (PMID 41030738, 2025). "Transcriptomic profiling further revealed elevated Cd8a and Ifng (markers of cytotoxic T cell infiltration/activity) alongside reduced Foxp3 (Tregs), Cd163 (M2-polarized tumor-associated macrophages), and Tgfb1 (immunosuppressive cytokine) in KO tumors." (PMID 41144132, 2025). "CD163+ M2 tumor–associated macrophages (TAMs) predominated, whereas CD4+ and CD8+ T cells were scarce, indicating an immune-suppressive microenvironment." (PMID 40469416, 2025). "A significant association was found between high CD163 expression in the tumor stroma of the primary tumor and positive hormone receptor status (p = 0.038)." (PMID 40510346, 2025). "The results showed a significant increase in CD163+ tumor-associated macrophages, which inversely correlated with relapse-free survival (RFS), progression-free survival (PFS), and OS." (PMID 40136652, 2025). "The impact of CD163+ tumor-associated macrophages representing the M2-anti-inflammatory type includes the production of a wide spectrum of growth factors, promoting cancer growth." (PMID 39936166, 2025). "Many recent studies have displayed the CD163-positive tumor-associated macrophages (TAMs) contribution in the pathogenesis of various hematological neoplasms and solid tumors." (PMID 39996747, 2025).
tumor (continued). "Along this line, we recently depicted that an increased count of CD163(+) macrophages in the tumor center is associated with dismal prognosis only in luminal type A but not in TNBC patients." (PMID 40243442, 2025). "Previous studies have positively correlated the tumor-infiltrating CD8+ T cell counts in SS with favorable outcomes, whereas for CD163+ tumor-associated macrophages (TAMs), the corresponding trend is negative." (PMID 41155410, 2025). "Lastly, evaluating the relationship between systemic cytokines and the tumor microenvironment revealed a significant association between IL‐10 and CD163+M2‐TAM expression (p < 0.05)." (PMID 41263059, 2025). "Regarding tumor-associated macrophages (TAMs), a recent study found that the geospatial clustering of CD163 + M2-polarized macrophages within the stromal compartment at the renal tumor margins was associated with poor clinical outcomes." (PMID 39751643, 2025). "On the other hand, the M2 type that has been known to be anti-inflammatory and immunosuppressive and tumor-associated macrophages (TAM) as well were assessed using immunohistochemical analysis of CD163, in addition to the genetic expression of Arg1 and Fizz1." (PMID 39949667, 2025). "In most HNSCC tumors, CD163+ macrophages and Tregs accumulate in large numbers at the tumor core and are closely associated with tumor progression." (PMID 40821122, 2025). "In human STS, co-infiltration of TAMs expressing both CD204 and CD163 at the tumor margins was associated with reduced disease-free survival (DFS), although the overall intratumoral percentage of these cells did not correlate with DFI." (PMID 41375061, 2025). "We found that the high expression of CD163-positive macrophages in the tumor stroma, was associated with an earlier occurrence of brain metastases (p = 0.015)." (PMID 40510346, 2025). "In HNSCC patients, high stromal expression of the tumor-associated macrophage marker CD163+ predicts poor prognosis." (PMID 40018039, 2025). "It is important to note that most tumor-associated macrophages in the PeCa TIME are CD68+CD163+ M2 macrophages." (PMID 40141426, 2025). "The percentage of myeloid-derived suppressor cells (MDSC) and CD163+ tumor-associated macrophages (TAM) were markedly downregulated in tumors expressing NPRL2, whereas the numbers of HLA-DR+ DC cells were significantly increased." (PMID 39932765, 2025). "In TNBC, M2-polarized tumor-associated macrophages (TAMs; CD163+) suppress effector T-cell function via ARG1, while exosomal LAP-TGF-β1 contributes to immunosuppression by reshaping the metastatic niche." (PMID 41573551, 2025). "Only one negative association was observed: When TLS were located within the tumor, this region comprised fewer CD163 + cells (considered as M2-like macrophages)." (PMID 40029549, 2025). "CD163+ tumor-associated macrophages (TAMs) play a significant role in the progression and microenvironment of oral tumor lesions." (PMID 40297579, 2025). "It is not surprising that these cathepsin-related functions so far only have been attributed to macrophages, given the phenotypic similarities between ti-DC3 and tumor-associated macrophages (e.g. CD163, CD14, CD11b expression)." (PMID 40789452, 2025). "In the HNSCC patients analyzed, elevated expression of CD16 and CD64 in tumor tissue was associated with improved prognosis, whereas high CD163 expression correlated with reduced five-year survival." (PMID 41181127, 2025). "Similar results were observed with the CD163+ marker, which also identifies M2-type macrophages and is commonly linked to advanced tumor stage and poor prognosis." (PMID 40498004, 2025). "High density of CD163-positive tumor-associated macrophages (TAMs) is associated with worse prognosis in various patient tumors." (PMID 40355384, 2025).
tumor (continued). "CD163 is a macrophage-specific protein hemoglobin specific for M2-tumor-associated macrophages, found at increased levels in stages III–IV, compared to stages I–II of CRC, and considered to be involved in immune suppression." (PMID 41450913, 2025). "The prominent increase in CD68+ and CD163+macrophages suggests their important role in tumor-associated immunomodulation." (PMID 41007741, 2025). "High levels of CD163 expression are associated with increased tumor cell proliferation, angiogenesis, and metastatic spread." (PMID 39857116, 2025). "CD163 serves as a marker for macrophage polarization, particularly in tumor-associated macrophages (TAMs)." (PMID 40427760, 2025). "They used CD68, a pan‐macrophage marker, and CD163, a marker of tumor‐associated macrophage class 2 (TAM‐2), which are considered tumor‐promoting due to their ability to facilitate tumor progression." (PMID 40736369, 2025). "Numerous studies have reported that CD163 is increased in different cancers and is associated with poor prognosis due to its tumor-promoting functions." (PMID 41395618, 2025). "Secondly, the M2-polarized macrophages are mainly composed of M2-like tumor-associated macrophages (TAMs) with tumor-promoting characteristics (CD163, FTH1, FTL, TIMP1), and there is a polarization from M1 to M2." (PMID 40948800, 2025). "In GD, GlcCer accumulation due to lysosomal β-glucocerebrosidase deficiency results in the persistent expression of tumor-associated macrophage markers (e.g., CD163), CD206-positive bone marrow mesenchymal stromal cells, and activated CD4+T cells." (PMID 41155172, 2025). "Using whole tumor slides, a slight decrease in tumor-associated CD163+(M2) macrophages and regulatory granulocytes was additionally shown." (PMID 40674934, 2025). "The expression of CD163 is associated with tumor-associated macrophages (TAMs), and thus, it has also been identified as a marker of worse prognosis in GBM." (PMID 40427760, 2025). "The study also indicated the presence of tumor macrophages (CD68+CD163+CSF1R+SIGLEC5+) associated with immunotherapy resistance." (PMID 40404633, 2025). "CD68 and CD163, for example, are tumor-associated macrophage (TAMs) markers, which recognizes M1 and M2 type macrophages." (PMID 39904885, 2025). "High CD163 expression in the tumor stroma of the primary was associated with RFS, while high CD86 expression in the tumor nest of brain metastases correlated with longer brain metastasis-specific survival." (PMID 40510346, 2025). "Another study demonstrated an association between CD163+ TAM (M2) infiltration at the TF tumor with EMT, the circulating tumor cells (CTCs) ratio, and poor prognosis in CRC patients." (PMID 40508145, 2025). "CD163 is a monocyte/macrophage scavenger receptor that is highly expressed on tumor-associated macrophages (TAMs) and is considered a macrophage activation marker." (PMID 39955339, 2025). "Conversely, CAFs are positively correlated with the cumulative density of regulatory T cells (Tregs) (Foxp3+), M2 tumor‐associated macrophages (TAMs) (CD163+), and potential Treg‐inducing immune cells (CD80+)." (PMID 39928309, 2025). "These cells present overexpressed inhibitory receptors, loss of effector function, and even the capacity to induce immune tolerance, and they are associated with an increased number of CD163+ cells in other tumor types as well." (PMID 39338178, 2024). "High B7-H3 expression in tumor cells was associated with a better prognosis and a significant increase in the number of CD163+PD-L1+ macrophages." (PMID 38893259, 2024). "After NK-LNP(PA/pDNA) treatment, M1 macrophage polarization markers associated with antitumor immunity (iNOS and CD86) were increased, while M2 macrophage markers associated with tumor progression (CD163 and CD206) were decreased compared to M0 macrophages." (PMID 39339179, 2024). "These populations include CD66b+ tumor-associated neutrophils (TANs), FoxP3+ Tregs, and CD163+ tumor-associated macrophages (AMs)." (PMID 38730579, 2024).
tumor (continued). "Consistent with the transcriptome data, mIHC results of tissue sections also demonstrated M2‐like tumor‐associated macrophages (TAMs) as the majority (CD163+ TAMs dominant)." (PMID 38896792, 2024). "Within the region corresponding to myeloid cells, there was separation between cells with highest expression for markers of microglia (TMEM119+ and P2RY12+) and tumor-associated macrophages (iba1+ and CD163+)." (PMID 38758780, 2024). "Elevated expression levels of CD47, CD68, and CD163 are commonly associated with a more immunosuppressive tumor microenvironment, which promotes tumor growth, metastasis, and resistance to treatment." (PMID 39682556, 2024). "IHC staining of F4/80 and CD163 indicated elevated levels of tumor-associated macrophages at the ablation border." (PMID 39659572, 2024). "CD163-positive macrophages, characteristic of the M2 alternatively activated macrophages, are associated with immunosuppression and tumor progression." (PMID 39072314, 2024). "We progressively detected the surface marker CD80 associated with M1 macrophages and CD163 associated with M2 macrophages to clarify the proportions of tumor macrophage subtypes." (PMID 38473271, 2024). "Only THBS2 and CD163 exhibited somatic mutations in 6.14% (25/407) and 5.90% (24/407) of patients with tumor, respectively, with the remaining genes showing mutation frequencies below 2%." (PMID 38577604, 2024). "CD163 is a marker of immunosuppressive polarization of tumor-associated macrophages, previously linked to GBM survival." (PMID 38805346, 2024). "TAMs are often identified by CD11b and CD68, with markers such as IFN-γ and HLA-DR associated with an anti-tumor phenotype, while CD163, CD206, PD-L1 and ARG1 are associated with a tumor-promoting phenotype." (PMID 39310770, 2024). "M1 (CD86+ CD163-) is a pro-inflammatory phenotype with anti-tumor activity, while M2 (CD86-CD163+) is an immunosuppressive cell type and is thought to have TAMs (tumor-associated macrophage) phenotype in solid tumors that can promote tumor progression." (PMID 38206974, 2024). "Some of the Ki-67+ CD163+ TAMs were found in the vicinity of blood vessels, closely associated with neighbouring tumour cells." (PMID 38903497, 2024). "Tumour-associated macrophages were analysed based on immunostaining of CD163 from biopsy and resection, with the percentage change in the resected tumour calculated across the entire NACT." (PMID 39273252, 2024). "We also examined the association of other variables, including age, tumor grade, multifocality, lymphovascular invasion, mortality, hormone status, with CD163 and FABP4 expression in tumor tissues." (PMID 39513934, 2024). "Specific targeting of CD163 TAMs (tumor-associated macrophages) mobilizes inflammatory monocytes and facilitates T cell-mediated tumor regression." (PMID 39068665, 2024). "We assessed the prognostic role of all tumor-associated macrophages, which express CD68, and their pro-tumor M2 subset, expressing CD163 individually and in combination." (PMID 38287290, 2024). "The Ki-67 proliferative activity marker and CD163 antibody on tumour-associated macrophages were assessed histologically." (PMID 38409583, 2024). "Several research works have shown that patients with a high load of tumor-associated CD163 macrophages are less likely to survive." (PMID 39594814, 2024). "High levels of infiltrating CD163+ tumor-associated macrophages are associated with a high risk of lymph node metastasis, while high levels of infiltrating CD206+ or CD68+ tumor-associated macrophages are associated with a better prognosis." (PMID 39087027, 2024). "Clinically, CD163 + TAMs infiltrating the tumor front are associated with EMT and poor prognosis in CRC patients." (PMID 39068459, 2024). "There is an established route through which infiltrating monocytes differentiate into immunosuppressive (CD163+ CD206+) tumor-associated macrophages that likely operates in parallel that we cannot address in our IMC data." (PMID 38758780, 2024).
tumor (continued). "Tumours with pro-angiogenic and pro-metastatic profile show high infiltration density of CD163 antibody on tumour-associated macrophages to produce significantly higher levels of anti-inflammatory cytokine interleukin-1022." (PMID 38409583, 2024). "The number of nuclei exhibiting positive staining with DAPI (blue) was designated as total cells, and CD68 (Cy3 red fluorescence) + CD86/CD163 (FITC green fluorescence) double fluorescent staining was utilized to label tumor-associated macrophages." (PMID 39531417, 2024). "TAN density correlated with CD163+ M2-like tumor-associated macrophage (TAM) density, which we analyzed in a previous study." (PMID 39335132, 2024). "Conversely, increased numbers of CD163+ macrophages are associated with poor prognosis, large tumor size, metastasis, distant recurrence, tumor progression, and decreased survival." (PMID 38600057, 2024). "CD163 + M2 TAMs always exhibit characteristics and functions associated with promoting tumor progression and are capable of secreting various cytokines that facilitate this process." (PMID 38951896, 2024). "Increased CD163-positive tumor-associated macrophages (TAMs) in the tumor microenvironment have been associated with tumor progression, metastasis, and poor prognosis in specific cancer types." (PMID 39682556, 2024). "We also found higher levels of the markers CD204 and CD163, which are associated with a pro-tumor phenotype of macrophages in HCC, in the tumor tissues of male patients compared to female patients." (PMID 39582864, 2024). "Tumor-associated macrophages (TAMs) demonstrated significant upregulation of CD163, CD68, and CSF1R." (PMID 39484208, 2024). "Among these, CD68 was found on all macrophages and monocytes, whereas CD163 is a high-affinity scavenger receptor and a marker of tumor-associated M2 macrophages." (PMID 39272860, 2024). "TAMs, defined as CD163+ cells in the tumor stroma and at the margin, were associated with worse survival." (PMID 38612926, 2024). "We detected expression of APOBEC2, infiltration of CD66b+ tumor-associated neutrophils and CD163+ tumor-associated macrophages in tissue microarrays by immunohistochemistry." (PMID 38166744, 2024). "Recently, CD11b+ tumor-infiltrating myeloid cells (TIMs) were shown to interact with other immune cells, especially CD163+ tumor-associated macrophages (TAMs) and CD8+ tumor-infiltrating lymphocytes (TILs), in the tumor microenvironment." (PMID 39452540, 2024). "There was also a positive correlation between tumor size and the number of CD163+ M2 macrophages (p = .005) and a positive association between the number of FoxP3+ Treg cells and the histological grade of the tumors (p = .042)." (PMID 38954689, 2024). "High H score values of CD163 staining showed significant associations with larger tumor size (p < 0.001), higher histological grade (p < 0.026), T3 tumor stage (p < 0.002) and advanced stage group (p < 0.001)." (PMID 39462379, 2024). "TIICs in the tumor microenvironment are assessed and quantified by categorizing immune cells into three subtypes: CD66b+ tumor-associated neutrophils (TANs), FoxP3+ regulatory T cells (Tregs), and CD163+ tumor-associated macrophages (TAMs)." (PMID 38730579, 2024). "In the myeloid compartment, stromal CD68+ tumour-associated macrophages (TAMs)were reduced in EC, whereas CD163+ M2 were increased." (PMID 39685707, 2024). "We previously reported that CD163-positive macrophages exert a tumor-promoting effect in undifferentiated pleomorphic sarcoma, with high CD163 expression associated with shorter overall survival." (PMID 38302407, 2024). "The spatial heterogeneity of lipid composition in the peri-tumoural region indicated tumour aggressiveness, and the spatial metrics of interaction between CD163 and cancer cells were associated with progression-free survival." (PMID 39273252, 2024).